RN7SKP83 (RN7SK pseudogene 83)
Gene: Miscellaneous RNA gene on chromosome 2 (85,820,435 to 85,820,612, reverse strand). Ensembl gene ENSG00000252321.
Homologues: Orthologues: chimpanzee 7SK (98% identical), guinea pig 7SK (58% identical). Paralogues in human: 7SK (72% identical), RN7SKP189 (72% identical), RN7SKP176 (71% identical), RN7SKP204 (71% identical), RN7SKP160 (71% identical), RN7SKP78 (71% identical), RN7SKP9 (71% identical), RN7SKP127 (70% identical), RN7SKP131 (70% identical), RN7SKP63 (70% identical), RN7SKP79 (70% identical), RN7SKP118 (70% identical), and 284 more.